LAMTOR2 (late endosomal/lysosomal adaptor, MAPK and MTOR activator 2)
Description:
As part of the Ragulator complex it is involved in amino acid sensing and activation of mTORC1, a signaling complex promoting cell growth in response to growth factors, energy levels, and amino acids. Activated by amino acids through a mechanism involving the lysosomal V-ATPase, the Ragulator plays a dual role for the small GTPases Rag (RagA/RRAGA, RagB/RRAGB, RagC/RRAGC and/or RagD/RRAGD): it (1) acts as a guanine nucleotide exchange factor (GEF), activating the small GTPases Rag and (2) mediates recruitment of Rag GTPases to the lysosome membrane. Activated Ragulator and Rag GTPases function as a scaffold recruiting mTORC1 to lysosomes where it is in turn activated. Adapter protein that enhances the efficiency of the MAP kinase cascade facilitating the activation of MAPK2 (By similarity).
Synonyms: MAPBPIP; ROBLD3; HSPC003; MAPKSP1AP; p14; ENDAP; Ragulator2
Tractability: Small molecule: a structure with a bound ligand is known. Antibody: its Gene Ontology location is reachable by antibodies, with high confidence; UniProt places it where antibodies can reach, with medium confidence. PROTAC: ubiquitination databases record sites on it; its protein half-life has been measured.
Gene: Protein-coding gene on chromosome 1 (156,054,738 to 156,058,510, forward strand). Ensembl gene ENSG00000116586.
Subcellular location: Late endosome membrane; Lysosome membrane
Subcellular location (Human Protein Atlas): Nucleoplasm; Vesicles
Pathways (Reactome):
Signal Transduction: Energy dependent regulation of mTOR by LKB1-AMPK; MAP2K and MAPK activation; MTOR signalling; Regulation of PTEN gene transcription; mTORC1-mediated signalling
Autophagy: Macroautophagy
Cellular responses to stimuli: Amino acids regulate mTORC1
Immune System: Neutrophil degranulation
Gene Ontology:
Molecular function: guanyl-nucleotide exchange factor activity; molecular adaptor activity; protein binding
Biological process: cellular response to amino acid stimulus; cellular response to nutrient levels; intracellular protein localization; positive regulation of TOR signaling; positive regulation of TORC1 signaling; regulation of cell growth; regulation of cell-substrate junction organization; TORC1 signaling; positive regulation of intracellular signal transduction
Cellular component: FNIP-folliculin RagC/D GAP; lysosomal membrane; Ragulator complex; endosome membrane; late endosome; late endosome membrane; plasma membrane; specific granule membrane; tertiary granule membrane; cytoplasm
Genetic constraint (gnomAD): Loss-of-function variants: 4 observed, 16.76 expected, observed/expected ratio (o/e) 0.24, 90% interval 0.12 to 0.55. The upper end of that interval is the gene's LOEUF score, 0.55, which puts it in group 2 of 6, group 1 being the genes least tolerant of losing a copy. Missense variants: 100 observed, 171.53 expected, observed/expected ratio (o/e) 0.58, 90% interval 0.5 to 0.69. Synonymous variants: 62 observed, 68.58 expected, observed/expected ratio (o/e) 0.9, 90% interval 0.74 to 1.12.
Homologues: Orthologues: chimpanzee LAMTOR2 (100% identical), guinea pig LAMTOR2 (100% identical), pig LAMTOR2 (100% identical), rabbit LAMTOR2 (100% identical), mouse Lamtor2 (99% identical), zebrafish lamtor2 (96% identical), dog LAMTOR2 (88% identical), macaque LAMTOR2 (88% identical), rat Lamtor2 (86% identical), Drosophila melanogaster Lamtor2 (70% identical), Caenorhabditis elegans lmtr-2 (37% identical).
Diseases named in the same sentence as LAMTOR2 in open-access papers:
LAMTOR2 is named in the same sentence as 26 diseases in open-access papers, as found by Europe PMC text mining. Sharing a sentence is not in itself a finding about the gene and the disease. The quoted sentences say what the papers report.
breast carcinoma (3 papers, 2013 to 2025). "Our aim was to address the possible role of genetic polymorphisms in LAMTOR2 and LAMTOR3 as genetic risk factors for breast cancer." (PMID 23341997, 2013). "Bioinformatic analysis of high-throughput cancer microarrays available on the public domain Oncomine revealed that LAMTOR2 (p14) is significantly up-regulated in breast cancer cells." (PMID 23341997, 2013). "We initially hypothesized that somatic, cancer-tissue-specific mutations in LAMTOR2 and LAMTOR3 could be associated with breast cancer progression and metastasis." (PMID 23341997, 2013). "Although the LAMTOR complex was independently demonstrated to be involved in breast cancer, neither LAMTOR2 nor LAMTOR3 came up as hits in genome-wide association studies (GWAS) with any kind of disease or trait as indexed by the catalogue of published GWAS." (PMID 23341997, 2013). "Therefore, future studies including a dense map of SNPs from the LAMTOR complex including the regulatory regions might reveal implications of genetic associations of LAMTOR2 and LAMTOR3 with breast cancer." (PMID 23341997, 2013). "We sequenced the exons and exon–intron boundaries of LAMTOR2 (p14) and LAMTOR3 (MP1) in 50 prospectively collected pairs of cancerous tissue and blood samples from breast cancer patients and compared their genetic variability." (PMID 23341997, 2013). "The identified polymorphisms in LAMTOR2 and LAMTOR3 do not seem to play a relevant role in breast cancer." (PMID 23341997, 2013). "Sequencing of the exons and exon-intron boundaries of both LAMTOR2 and LAMTOR3 revealed three SNPs to occur in a sequencing sample of 50 breast cancer patients, but no novel mutations." (PMID 23341997, 2013). "The present work does not exclude that the observed polymorphisms may play a role in other disease contexts or that other not yet identified polymorphisms in LAMTOR2 and LAMTOR3 may in fact contribute to breast cancer aetiology." (PMID 23341997, 2013).
Salmonella Infections (3 papers, 2014 to 2024). Infections with bacteria of the genus SALMONELLA. "Along those lines go observations that mice with LAMTOR2-deficient macrophages cannot properly fight Salmonella infections due to defects in their phagosomal compartment." (PMID 25336251, 2014). "In addition, they identified LAMTOR2 and LAMTOR1 as previously overlooked xenophagy regulators of TAX1BP1 in response to Salmonella infection, and confirmed that LAMTOR2 was recruited to damaged SCVs via LAMTOR1, an endosome-resident protein." (PMID 32390979, 2020).
prostate carcinoma (2 papers, 2012 to 2015). A carcinoma that arises from epithelial cells of the prostate gland. "ADP-ribosylation factor-like 8b (ARL8B), among the enriched proteins in prostate cancer patients urinary exosomes, has been associated with the LAMTOR complex too, in particular with LAMTOR2/3 and its role in cell migration." (PMID 26196085, 2015).
Alzheimer disease (1 paper, 2017). A progressive, neurodegenerative disease characterized by loss of function and death of nerve cells in several areas of the brain leading to loss of cognitive function such as memory and language. "LAMTOR2 complex regulated focal adhesion dynamics during cell migration and CLK2 was proved to change in Alzheimer's disease." (PMID 28938616, 2017).
COVID-19 (1 paper, 2022). A disease caused by infection with severe acute respiratory syndrome coronavirus 2. "However, more needs to be done to examine the exact role of LAMTOR2 in platelets of COVID-19 patients." (PMID 35421970, 2022).
craniosynostosis (1 paper, 2018). Craniosynostosis is defined as the premature fusion of one or more cranial sutures leading to secondary distortion of skull shape resulting in skull deformities with a variable presentation. "Out of seven genes with a high (< 10%) or moderate (< 25%) HI score (NES, CCT3, MEF2D, LAMTOR2, ETV3, SSR2, NTRK1), none of them have been linked to craniosynostosis." (PMID 29845577, 2018).
malnutrition (1 paper, 2022). Inadequate nutrition resulting from poor diet, malabsorption, or abnormal nutrient distribution. "The deregulation in the activity of the TSC1 and LAMTOR2 gene was significantly associated with all forms of childhood malnutrition." (PMID 35458174, 2022).
primary immunodeficiency diseases (1 paper, 2022). "Moreover, the p14/LAMTOR2 deficiency- which is associated with one of the primary immunodeficiency diseases that also include “Hermansky–Pudlak syndrome type 2”- has been linked to platelet defects." (PMID 35421970, 2022).
Sepsis (1 paper, 2020). Sepsis is defined as life-threatening organ dysfunction caused by a dysregulated host response to infection. "To further investigate the role of LAMTOR2 in K. pneumoniae-induced sepsis, we first investigated whether bacterial loads were altered in Lamtor2−/− RAW264.7 macrophages." (PMID 33144310, 2020).
cancer (5 papers, 2013 to 2025). A tumor composed of atypical neoplastic, often pleomorphic cells that invade other tissues. "Particularly, the key regulators of mTOR signaling such as LAMTOR2, LAMTOR5, YWHAB, LAMTOR1, FKBP1A, and RHEB were also upregulated in the cancer cells of intra‐tumoral TLS‐low group." (PMID 38498682, 2024).
tumor (4 papers, 2013 to 2024). "The experimental conclusion about LAMTOR2-mediated VSIG2 oncogenic effect on PDAC was ulteriorly elucidated using subcutaneous xenograft tumor model." (PMID 37626304, 2023). "Nonetheless, over-expressed LAMTOR2 or supplement of MHY1485 accelerated tumor growth." (PMID 37626304, 2023). "We found one single nucleotide polymorphism (SNP) in LAMTOR2 (rs7541) and two SNPs in LAMTOR3 (rs2298735 and rs148972953) in both tumour and blood samples, but no somatic mutations in cancerous tissues." (PMID 23341997, 2013). "Besides, tumor weight was recorded and analyzed after dissection, the role of VSIG2 depletion in tumor weight was impaired after elevation of LAMTOR2 or supplement of mTOR activator, indicating that VSIG2 advanced PDAC progression through LAMTOR2-mediated mTOR activation." (PMID 37626304, 2023). "Our hypothesis that LAMTOR2 and LAMTOR3 gene regions would harbour somatic mutations in tumour tissue was not confirmed; all SNPs that were found were present in both benign (DNA derived from whole blood) and cancerous tissue." (PMID 23341997, 2013).
neurodegenerative disease (1 paper, 2023). A disorder of the central nervous system characterized by gradual and progressive loss of neural tissue and neurologic function. "It was shown that enhanced autophagy was associated with extended lifespan in model organisms (such as worm and mouse), and increasing evidences indicated that several genes (including LAMTOR4, LAMTOR2 and NPRL3) involved in mTOR network regulated autophagy and neurodegenerative diseases." (PMID 37582720, 2023).
LAMTOR2 also shares sentences with these, for which no sentence is quoted: Congenital neutropenia (2 papers); pancreatic ductal adenocarcinoma (2); 3-methylglutaconic aciduria (1); Autoimmunity (1); Barth syndrome (1); Chediak-Higashi syndrome (1); Cohen syndrome (1); glycogen storage disease type 1b (1); Griscelli syndrome type 2 (1); Immunodeficiency (1); Insulin resistance (1); nervous system diseases (1); neutropenia (1); testis cancer (1).